KLRG1 (killer cell lectin like receptor G1)
Description:
Plays an inhibitory role on natural killer (NK) cells and T-cell functions upon binding to their non-MHC ligands. May mediate missing self recognition by binding to a highly conserved site on classical cadherins, enabling it to monitor expression of E-cadherin/CDH1, N-cadherin/CDH2 and R-cadherin/CDH4 on target cells.
Synonyms: CLEC15A; MAFA; 2F1; MAFA-L; MAFA-2F1; MAFA-LIKE
Tractability: Antibody: UniProt places it where antibodies can reach, with high confidence; UniProt predicts a signal peptide or a membrane-spanning region; its Gene Ontology location is reachable by antibodies, with medium confidence.
Gene: Protein-coding gene on chromosome 12 (8,950,044 to 9,010,760, forward strand). Ensembl gene ENSG00000139187.
Subcellular location: Cell membrane
Subcellular location (Human Protein Atlas): Vesicles
Pathways (Reactome):
Immune System: Immunoregulatory interactions between a Lymphoid and a non-Lymphoid cell
Gene Ontology:
Molecular function: protein binding; carbohydrate binding; signaling receptor activity
Biological process: cell surface receptor signaling pathway; cellular defense response; inflammatory response
Cellular component: membrane; plasma membrane
Genetic constraint (gnomAD): Loss-of-function variants: 11 observed, 14.53 expected, observed/expected ratio (o/e) 0.76, 90% interval 0.48 to 1.25. The upper end of that interval is the gene's LOEUF score, 1.25, which puts it in group 5 of 6, group 1 being the genes least tolerant of losing a copy. Missense variants: 139 observed, 184.38 expected, observed/expected ratio (o/e) 0.75, 90% interval 0.66 to 0.87. Synonymous variants: 55 observed, 65.13 expected, observed/expected ratio (o/e) 0.84, 90% interval 0.68 to 1.06.
Homologues: Orthologues: chimpanzee KLRG1 (97% identical), macaque KLRG1 (91% identical), rabbit KLRG1 (72% identical), pig KLRG1 (69% identical), guinea pig KLRG1 (67% identical), dog KLRG1 (65% identical), mouse Klrg1 (57% identical), rat Klrg1 (54% identical), Caenorhabditis elegans clec-196 (12% identical). Paralogues in human: KLRF1 (29% identical), CLEC12B (28% identical), OLR1 (28% identical), CLEC9A (26% identical), KLRB1 (25% identical), KLRC1 (25% identical), CLEC12A (24% identical), KLRC2 (24% identical), KLRG2 (24% identical), CLEC1A (24% identical), CLEC7A (24% identical), KLRC3 (23% identical), and 11 more.
Diseases named in the same sentence as KLRG1 in open-access papers:
KLRG1 is named in the same sentence as 119 diseases in open-access papers, as found by Europe PMC text mining. Sharing a sentence is not in itself a finding about the gene and the disease. The quoted sentences say what the papers report.
viral infection (34 papers, 2011 to 2024). "T-bet, which has been shown to sustain exhausted CD8+ T cells during chronic viral infection, was also highly expressed in the KLRG1+ CD8+ T cells." (PMID 38776335, 2024). "Studies targeting KLRG1 have shown that KLRG1 not only serves as a marker of T-cell senescence but also increases with disease severity in autoimmune, viral infections and cancer, and can serve as a biomarker for assessing disease progression and prognosis." (PMID 38898461, 2024). "Further unbiased investigation into the most expressed genes per cluster revealed a plethora of genes previously reported in the context of viral infections, such as Il7r, Tcf7, Zeb2, Klrg1, Gzma, Gzmb, Gzmk, Vim, Lgals3, Tox, Lag3, Pdc1, Id3." (PMID 35185882, 2022). "It is known that the PD-1/PDL-1 or PDL-2 axis plays an essential role in immunity against viral infections, whereas E-cadherin/KLRG1 axis regulates the activation of NK and NKT cells in viral infections." (PMID 35053573, 2022). "Recently, it was shown that viral infections induce the expression of checkpoint receptors like programmed death-1 (PD-1) and killer cell lectin-like receptor G1 (KLRG1) on NK and NKT cells, regulating the activation of these cells." (PMID 35053573, 2022). "Next, we analysed the expression of markers associated with T cell differentiation and memory formation (CD27, CD127, KLRG1) post-burn and viral infection." (PMID 35505970, 2022). "Inflammation has been shown to promote T‐bet expression in activated CD8+ T cells during viral infection, which subsequently controls KLRG‐1 expression." (PMID 34407221, 2021). "KLRG1+ CD8TTEs are frequently expanded in response to viral infections and produce IFN-γ but are also found in patients with autoimmune disease and cancer as dysfunctional T cells in persistent inflammatory conditions." (PMID 34375314, 2021). "More recently, senescent T cells have been identified by the expression of KLRG-1 or CD57 in the context of aging or viral infection." (PMID 34386013, 2021). "Intriguingly, differential expression of the activating receptor, KLRG1, by effector T and NK cells has been shown to distinguish cells with effector vs. memory cell potential at early stages of a viral infection." (PMID 32269968, 2020). "An inverse relationship between Tox and Klrg1 expression in CD8 T cells during viral infection has been reported, and Klrg1 expression correlates with T-bet levels." (PMID 33584701, 2020). "During acute viral infections in mice, IL‐7Rα and KLRG1 together are used to distinguish the short‐lived effector cells (SLEC; IL‐7RαloKLRGhi) from the precursors of persisting memory cells (MPEC; IL‐7RαhiKLRG1lo)." (PMID 30883723, 2019). "During acute viral infection in mice, KLRG1 is a marker for short-lived effector CD8+ T-cells." (PMID 38898461, 2024). "Effector CD8+ T cells that infiltrated VacV-infected skin were predominately KLRG1- compared with T cells in the spleen, suggesting KLRG1- effector CD8+ T cells may preferentially traffic into the skin during an acute viral infection." (PMID 37402742, 2023). "In a previous report, Klrg1+ Cd27+ cells demonstrated robust cytotoxicity against viral infection." (PMID 37638012, 2023). "Human CD8 T cells from virus infection highly expressed KLRG1 which may be related with the increased incidence of infectious diseases." (PMID 27557510, 2016). "It has been reported that the expression of KLRG1 on human CD8+ T cells was elevated in the condition of virus infection, which may contribute to increased morbidity of infectious diseases." (PMID 27557510, 2016). "In addition, the expression level of KLRG1 significantly increased after virus infection in mice." (PMID 38898461, 2024). "Together with the CD45RO− CD127− and KLRG1+ phenotypes in this group, these findings indicate that IFNλ4 non-producing patients display larger numbers of T cells with senescent and exhausted phenotypes typical of chronic immune activation in response to viral infection." (PMID 33158978, 2021).
viral infection (continued). "After viral infection, the ability of mouse NK cells to produce interferon-γ (IFN-γ) is negatively correlated with KLRG1 expression." (PMID 38898461, 2024). "Consistent with an increase of T cell exhaustion in chronic as compared to acute viral infections, we found increased frequencies of TIGIT+KLRG1+ TEX in CMV- and EBV-specific T cells identified by pentamer reagents as compared to influenza-specific T cells." (PMID 38650930, 2024). "Our data suggested that NFATc1 signaling promotes KLRG1+CD27- T cell differentiation and memory inflation during chronic virus infection." (PMID 38346075, 2024). "During chronic viral infections, senescent T cells express CD57, KLRG1, and killer cell immune globulin-like receptors and are capable of producing a significant amount of effector cytokines." (PMID 33351781, 2021). "It is well documented that KLRG1 is upregulated on CD8+ T cells during both viral and parasitic infections, and its expression is maintained on CD8+ T cells post viral infection." (PMID 27302925, 2016). "Klrg1 is expressed on NK cells and effector CD8 T cells during acute viral infection." (PMID 33584701, 2020). "In these individuals that had no clinical and/or laboratory signs of acute viral infection, we detected substantial numbers of KLRG1‐expressing cells." (PMID 30883723, 2019). "Acute viral infection induces naive CD8+ T cells to differentiate into short-lived effector cells (SLEC) or memory-precursor effector cells (MPEC), which are distinguishable by the levels of cell surface expression of KLRG-1 (Killer cell lectin-like receptor subfamily G member 1) and CD127." (PMID 27171004, 2016). "We observed a subset of cells that did not express CD127 but co-expressed Tim-3 and KLRG1 as well as T cell factor 1 (TCF1), which has been recently shown to sustain memory function during chronic viral infections." (PMID 31145756, 2019).
breast cancer (17 papers, 2013 to 2024). A primary or metastatic malignant neoplasm involving the breast. "CDH1 mutation in breast cancer defines a NK cell infiltrated/activated TME type by releasing the inhibition from NK cell inhibitory receptor KLRG1." (PMID 38241355, 2024). "In a mouse model of breast cancer, the combination of an anti-KLRG1 antibody with a DNA methyltransferase inhibitor further reduced the metastatic potential of breast cancer and effectively prevented metastatic recurrence compared to use of the antibody alone." (PMID 38898461, 2024). "In a mouse model of breast cancer, antibody neutralization of KLRG1 reduced the formation of tumor colonies, significantly increased the antitumor activity of tumor-infiltrating cells and peripheral T-cells, and reduced lung metastasis." (PMID 38898461, 2024). "In a 4T1 breast cancer model, an anti-KLRG1 antibody inhibited the binding of mouse E-cad to KLRG1 and significantly reduced lung metastasis." (PMID 38898461, 2024). "In a mouse model of breast cancer, antibody neutralization of KLRG1 significantly increased the antitumor activities of tumor-infiltrating T-cells and PB T-cells and significantly reduced lung metastasis." (PMID 38898461, 2024). "In breast cancer patients, killer cell lectin-like receptor G1 (KLRG-1)+CD57+CD4+ and CD8+ senescent T cells that produce more effector cytokines, granzyme B and perforin accumulate in peripheral blood and in the tumor." (PMID 35326515, 2022). "To explore the possible contribution of the KLRG1+CD57+ CD4+ T cell subset in the clinical prognosis of breast cancer, we collected publicly available TCGA datasets of patients with breast carcinoma to link gene expression data with overall survival (OS)." (PMID 34386013, 2021). "Anti-KLRG1 neutralizing antibody was studied in the murine 4T1 breast cancer as monotherapy, and in the MC38 colon cancer and B16F10 melanoma models as combination therapy with anti-PD-1 antibody." (PMID 30858925, 2019). "E-cadherin expression associated to ER+ breast carcinomas dampens trastuzumab-dependent ADCC through its specific interaction with the inhibitory killer cell lectin-like receptor G1 (KLRG1) on NK cells in preclinical in vitro and in vivo models." (PMID 29181007, 2017). "Indeed, the combination of anti-KLRG1 with other inhibitors can improve the antitumor response in mice with melanoma, further reducing the metastatic potential of breast cancer and effectively preventing metastatic recurrence." (PMID 38898461, 2024). "Hence, KLRG1 is likely the major inhibitory receptor engaged by necroptosis to inhibit the anti-tumor activity of T cells in MMTV-PyMT breast cancer model." (PMID 36703228, 2023). "Moreover, as a contributor of functional switch into a pro-tumoral NK cell state, KLRG1 is highly expressed in the TME of breast cancer lymph node metastases." (PMID 36148946, 2022). "Moreover, coinhibition of Klrg1 and PD‐1 improves immunity to melanoma, colorectal, and breast cancer." (PMID 32383488, 2020). "We confirmed that anti-KLRG1 antibody inhibited binding of mouse E-cadherin to KLRG1 and tested its effect on preventing metastasis in the 4T1 metastatic breast cancer model." (PMID 30858925, 2019). "The expression of CD4, KLRG-1, and CD57 correlates with increased overall survival for breast cancer patients." (PMID 35326515, 2022). "KLRG1 in LUAD and melanoma can serve as a marker for detecting the response to treatment with immune checkpoint inhibitors and has the potential to be a therapeutic target in breast cancer, melanoma, and CRC." (PMID 38898461, 2024).
melanoma (17 papers, 2011 to 2026). A malignant, usually aggressive tumor composed of atypical, neoplastic melanocytes. "However, a reduced B16 melanoma cell line metastatic burden was observed in KLRG1-deficient mice compared with wildtype controls, confirming the inhibitory function of KLRG1 in the anti-tumor immune response." (PMID 34885076, 2021). "Therefore, we showed here for the first time that the degree and quality of melanoma-associated effector memory KLRG1+CD8+ T cells can play an important role for controlling and/or resolving tumors." (PMID 28388572, 2017). "In mouse melanoma-related NK cells, a decrease in KLRG1 expression leads to a decreased proliferative capacity of intratumoral NK cells." (PMID 38898461, 2024). "In a melanoma mouse model, the use of an anti-KLRG1 antibody alone moderately depleted intratumoral Tregs but not peripheral Tregs, which prevented the autoimmune side effects caused by systemic depletion of Tregs." (PMID 38898461, 2024). "These “exKLRG-1 memory cells” have been demonstrated to inhibit tumor growth more efficiently than KLRG-1+ cells in an OT-I melanoma mouse model." (PMID 39190688, 2024). "In line with this are findings in the TME of melanoma patients, where KLRG1 was found to be expressed in the cytotoxic T cell compartment." (PMID 36796366, 2023). "Adoptive transfer of KLRG1+CD8 T cells showed a stronger protection against B16 melanoma cells than KLRG1−CD8 T cells." (PMID 31664180, 2019). "By Day-25 nearly all the CD8+ T-cells and the majority of CD4+ effector T-cells infiltrating the B16 melanoma tumors of α4-1BB and α4-1BB/αCTLA-4 treated mice are KLRG1+." (PMID 21559358, 2011). "Like the CD8 T-cells, the effector CD4+ T-cells infiltrating B16 melanoma expressed much higher levels of KLRG1 and PD-1 in response to α4-1BB or combination therapy." (PMID 21559358, 2011). "In MC38 colon cancer and B16F10 melanoma models, combination therapy of anti-KLRG1 and anti-PD-1 antibodies inhibited tumor growth and synergistically reduced tumor volume more than treatment with anti-KLRG1 or anti-PD-1 antibody controls alone." (PMID 38898461, 2024). "To further investigate the role of c-Met+ CTLs in a three-dimensional (3D) setting, we studied their function within B16 melanoma spheroids and examined the impact of cell–cell contact on the modulation of inhibitory checkpoint molecules’ expression, such as KLRG1, PD-1, and CTLA-4." (PMID 38137344, 2023). "Further investigation showed that even in mice injected with 5 × 104 melanoma cells, KLRG1+CD8 T cells could also expand in numbers as effectively as in mice with 5 × 102 melanoma cells." (PMID 31664180, 2019). "Confirming our results on paraffin sections, E-cadherin expression was infrequent on melanoma cell lines, in line with the known E-cadherin downregulation by metastatic tumor cells and corresponding to the diminished expression of KLRG-1 by CD8 T-cells found in TILN." (PMID 22347406, 2012). "Also, topical administration resulted in an increased expression of some markers for NK cell activation and maturation, such as CD69, NKp46, CD122, CD11b, CD43, KLRG1, and CD27, when compared with melanoma-bearing mice." (PMID 41597427, 2026). "Increased values were also observed for CD27 and B220 compared to the control group, but not the melanoma group, while KLRG1 expression was higher than for the melanoma group, approaching that of healthy animals." (PMID 41597427, 2026). "A benefit for KLRG1 blockade in mouse models was demonstrated in 2019 and again in 2021, with KLRG1 and PD-1 blockade producing supra-additive benefits in the B16F10 mouse melanoma model." (PMID 39832302, 2025). "The absence of KLRG1 signaling alone significantly reduced the growth of melanoma and breast cancer tumors in mouse lungs." (PMID 38898461, 2024).
melanoma (continued). "In the MC38 colon cancer and B16F10 melanoma models, monotherapy with KLRG1 was not significantly different than anti-PD-1 therapy, but combination therapy showed significant efficacy, including 10% of mice showing tumor regression and durable cure." (PMID 30858925, 2019). "Here, we show that the enhanced induction of tumor-specific KLRG1+CD8+ effector memory T cells in the blood, spleen, and tumors correlated with the better efficacy of the Vax/aGITR/aPD-1 treated groups against established melanoma tumors." (PMID 28388572, 2017). "Taken together, these results suggest that the increase of Ag-specific KLRG1+ effector CD8+ T cells induced by the triple combination was a mechanism by which it facilitated tumor growth control, regression, and long-term survival in this melanoma therapeutic model." (PMID 28388572, 2017).